ATF3 (activating transcription factor 3)
Diseases named in the same sentence as ATF3 in open-access papers (continued):
Sharing a sentence is not in itself a finding about the gene and the disease.
cancer (238 papers, 2001 to 2026). A tumor composed of atypical neoplastic, often pleomorphic cells that invade other tissues. "Other studies have also indicated that stress-induced ATF3 can bind to the promoter regions of GADD45 family members to activate them, while cancer-associated ATF3 can repress them." (PMID 40332279, 2025). "NR2F1’s involvement in EMT and chemoresistance, along with ATF3’s association with heightened treatment resistance, rendered these factors pivotal in cancer progression." (PMID 40612060, 2025). "Again, the FLNA editing state affected the expression of proliferation-, cancer-, and stress response–associated genes (Junb, Jun, Pard6b, Atf3, Hspa1a and -b, Cyp2c55, and Abcb1a)." (PMID 40471139, 2025). "We have previously demonstrated that ATF3 is upregulated in the intratumoral monocytic cells in human cancers, and high levels of ATF3 in this compartment are associated with poor prognosis." (PMID 36333297, 2022). "TP63 is a classical marker of squamous differentiation in cancer, and our studies suggest ATF3 induction is associated with TP63 expression in invading endometrial epithelial cells following ARID1A loss." (PMID 34941867, 2021). "Initially identified as a suppressor of inflammation and the adaptive immune response in resting cells, ATF3 is now associated with numerous diseases including a variety of aggressive and widely occurring cancers." (PMID 28186491, 2017). "Activating transcription factor 3 (Atf3) is an important regulatory transcription factor which is associated with inflammation, restraint of the immune response and cancer." (PMID 24811474, 2014). "The bzip TF ATF3 has been implicated as a key regulatory molecule in pathological states as cancer and the inflammatory response." (PMID 24875474, 2014). "Particular emphasis is placed on its role in inflammation and Atf3 is essential for restraining the immune response, but Atf3 is also associated with cancer and cardiac dysfunction." (PMID 24811474, 2014). "In breast cancer, ATF-3 enhances cancer cell-initiating features and is associated with activation of the canonical Wnt/β-catenin pathway." (PMID 24222778, 2013). "Cisplatin, an anti-cancer drug that causes nephrotoxicity, has been previously shown to induce cytotoxicity via activating transcription factor 3 (ATF3) together with the MAPK pathway." (PMID 23028726, 2012). "We show that stress-induced and cancer-associated ATF3 is recruited to 5,984 and 1,423 targets, respectively, in the human genome, 89% of which are common." (PMID 22046379, 2011). "The number of targets of cancer-associated ATF3 was smaller than that of DNA damage-induced ATF3, perhaps reflecting both higher levels and greater fold-induction of ATF3 in MMS response than those achieved by knockdown of ATF3 in LNCaP cells (data not shown)." (PMID 22046379, 2011). "Next, to identify potential targets of ATF3 in cancer-associated ATF3, we carried out ATF3 knockdown and expression profiling using LNCaP cells." (PMID 22046379, 2011). "Notably, MP7 was associated with stress meta program (MP5) in pan‐cancer studies, sharing 14 common genes, including ATF3, EGR1, FOSB, GADD45B and NR4A1." (PMID 40292733, 2025).
cancer (continued). "Most early induced NF-κB target genes associated with cancers (such as Tgif1,2 and Atf3,4) were also Rel-responsive, indicating that early and late Rel target genes may drive oncogenesis." (PMID 37524800, 2023). "In addition, some evidence has implicated that ATF3 is up-regulated in many cancers, suggesting that ATF3 is an oncogene." (PMID 34768829, 2021). "Moreover, ATF3 is induced by stress stimuli and associates with various kinds of cancer development." (PMID 32093223, 2020). "The sensitization of primary afferent fibres that innervate cancer-bearing bones in the early stage of disease was linked in the present study with a high expression of cellular stress marker activating transcription factor 3 (Atf3)." (PMID 33172040, 2020). "In addition, a solid line of evidence has indicated that ATF3 is able to suppress cell growth and inhibit the development of tumors; however, some evidence has implicated that ATF3 is up-regulated in many cancers, suggesting that ATF3 is an oncogene." (PMID 32093223, 2020). "ATF3 has been implicated in the regulation of cellular invasion in several cancer entities." (PMID 33050633, 2020). "Interesting for cancer research, it is the fact that Sall2 deficiency increases the growth rate, foci formation, and ability of immortalized MEFs to form colonies in soft agar, similar to the effect of knocking out ATF3, an inhibitor of cyclin D1." (PMID 29689621, 2018). "Early studies indicated Cisplatin's anticancer activity was associated with its DNA damaging effects and induction of cancer cell apoptosis, that might involve altering various signal transduction pathways, including activating ATF3 signaling pathways." (PMID 27050071, 2016). "Deregulation of actin bound proteins, namely p38β, ATF3 and Rho family of small GTPases which are involved in cytoskeletal remodelling, causes aberrant cell motility that leads to the muscle-invasive and metastatic phenotypes in cancer." (PMID 25569276, 2015). "Overall, the results suggest that ATF3 plays several functional roles in cancer development and immune regulation, but the underlying mechanism remains largely unknown." (PMID 23591848, 2013). "Cancer-associated ATF3, by contrast, represses these pro-apoptotic genes in addition to CDKN1A/p21." (PMID 22046379, 2011). "Rather, effects of ATF3 on many but select genes, such as those involved in cell cycle and cell death, collectively amounted to biologically significant outcome as cell death for ATF3 in stress response or cell growth for cancer-associated ATF3." (PMID 22046379, 2011). "Because the anti-cancer activity of the CTX-treated Atf3 KO macrophage is associated with its high expression of cathelicidin, a cytotoxic antimicrobial peptide, we posit that cathelicidin may have the potential to dampen the pro-cancer effect of chemotherapy." (PMID 34298975, 2021). "ATF3, a transcription factor known for its role in stress responses and inflammation 25, 26, has recently emerged as a potential target in cancer therapy." (PMID 41438581, 2026). "ATF3 was discovered to be a dichotomous molecule that helps cancer cells evade apoptosis or cell cycle arrest by thwarting the harmful stress response." (PMID 40016181, 2025).
cancer (continued). "Similar comparisons between APK and wild type acini revealed none of these gene sets were enriched, supporting a role for ATF3 in KRASG12D’s ability to initiate cancer progression." (PMID 41198649, 2025). "More research is needed to fully comprehend the role that ATF3 plays in alternative splicing of other genes and the adaptability of cancer cells to hypoxia." (PMID 40016181, 2025). "Notable downregulated genes included Mki67, Ccn1, Muc1, Atf3, Ntrk2, Arid5b, Igf1r, Igf2bp2, Cd47, and Cd37 (oncogenic function) and integrin-related genes, Itga7, Itga11, Itgam and Notch1 (cancer stem cell markers)." (PMID 39946195, 2025). "In recent years, the role of ATF3 in cancer has been extensively studied, with conflicting reports suggesting its dual nature." (PMID 40837407, 2025). "Published reports show ATF3 promotes progression in other cancers and mediates KRAS signaling directly." (PMID 41198649, 2025). "The functions of ATF3 in glucose metabolism, adipocyte differentiation, regulation of immune responses, host defences and cancers have been extensively studied." (PMID 39827141, 2025). "In the context of cancer cells, ATF3 was demonstrated to have differential roles across various cancer types." (PMID 38586033, 2024). "Given that ATF3 functions in multiple pathways to regulate cancer progression, we proposed that ATF3 is a key downstream gene regulated by TRIM24 in the TRIM24‐driven Ep‐GBM‐like transformation." (PMID 38828688, 2024). "We further provide evidence that FADS1 is essential for supporting cancer cell growth by protecting cancer cells from persistent ER stress, which is mediated by a key transcription factor ATF3." (PMID 38586033, 2024). "Following ATF3 expression, SERPINE2 causes the improvement of cell colony-forming capacity and is thus involved in the control of cancer growth." (PMID 37124542, 2023). "Activating transcription factor 3 (ATF3) is induced by a variety of stress signals and regulates apoptosis as well as controls immune responses and inflammation in cancer." (PMID 36131935, 2022). "Several studies have indicated that ATFs act as an oncogene in CRC, for example, the induction of ATF3 contributes to anti-cancer activity of Abeliophyllum distichum Nakai in human CRC cells." (PMID 35034547, 2022). "In this study, we showed that C. majus induces apoptosis of SKOV-3 cancer cells through Foxo3a signaling mediated by ATF3 and Tip60." (PMID 35283423, 2022). "Here, RNA sequencing and experimental studies show that transcription factor ATF3 as a key regulator of cellular stress response is upregulated in cancer cells after treatment with Gemini-Cur." (PMID 35684411, 2022). "One potential regulator is ATF3, a transcription factor that is involved in the host response to inflammation, infection and cancer." (PMID 35371105, 2022). "Activating transcription factor 3 (ATF3) is a transcription factor related to the proliferation and metastasis of cancer cells." (PMID 35871061, 2022). "In the top 20 upregulated DEGs of lymph node‐derived exhausted CD8+ T cells, CXCL13, CXCR4, CH25H, HSPD1, HSP90AA1, and ATF3 have been confirmed to promote lymph node metastasis in several cancer types." (PMID 35184420, 2022). "Previously, we showed that chemotherapy paradoxically exacerbated cancer cell colonization at the secondary site in a manner dependent on Atf3, a stress-inducible gene, in the non-cancer host cells." (PMID 34298975, 2021). "In response to chemotherapy, the wild-type (WT) macrophages exhibit a pro-cancer activity, but the Atf3 KO macrophages an anti-cancer activity." (PMID 34298975, 2021).
cancer (continued). "In our most recent studies, we further discovered direct regulation of Nrf2 on several growth factors critical for cancer cell growth and proliferation, Nrf2 dependent ATF3 expression, and possible different or uncharacterized Nrf2 isoforms." (PMID 35052581, 2021). "To narrow down the factors relevant to the ability of CTX to increase EC adhesiveness, we took advantage of the observation that CTX increased the abundance of cancer cells in both WT and Atf3 KO lungs at 3 h after cancer cell injection (and Introduction)." (PMID 34638621, 2021). "ATF3 has been reported to be dysregulated in various cancers and involved in various steps of tumorigenesis." (PMID 34728784, 2021). "The ATF3 pathway is involved in many cellular processes that are related to fibrosis and to the development of cancer." (PMID 34769496, 2021). "The rationale for investigating Atf3 in macrophage is two-fold: (a) macrophage plays an important role in cancer progression (reviews); (b) macrophage is a key cell type for Atf3 function." (PMID 34298975, 2021). "Overexpression of ATF3 highly regulated the cell cycle, estrogen signaling pathway, cAMP signaling pathway, cytokine–cytokine receptor signaling pathway, and microRNAs in cancer pathways." (PMID 33846304, 2021). "ATF3 has been reported to be involved in many pathological conditions, such as cancer, infections/inflammation, diabetes, and ischemic injury of the heart, liver, or brain." (PMID 33816467, 2021). "We also found that overexpression of ATF3 significantly changed the microRNAs in the cancer pathway." (PMID 33846304, 2021). "Previous studies have indicated that ATF3 can upregulate DR5 expression in the context of anti-cancer agents camptothecin (CPT), celecoxib and zerumbone, as well as environmental carcinogen tetrachlorobenzoquinone (TCBQ)." (PMID 33921748, 2021). "On the other hand, several studies substantiate the down-regulation of ATF3 in cancers and support it as a suppressor in oncogenesis." (PMID 34098867, 2021). "Since injuries and surgeries are stressors, we posit that these stressors induce Atf3, which in turn creates a cancer-friendly host environment (as shown in our data above), allowing residual cancer cells to thrive." (PMID 34298975, 2021). "Analysis of gene expression profiles in FTS-treated cancer cells points to the upregulation of stress response genes, such as ATF3 and ATF4." (PMID 33676427, 2021). "In summary, the status of Atf3 dictates the dichotomous activity of macrophage: pro-cancer for CTX-treated WT macrophage but anti-cancer for the KO counterpart." (PMID 34298975, 2021). "Depleting macrophages from CTX-treated Atf3 KO mice (group 4) resulted in less cancer cell apoptosis, indicating that these macrophages (Atf3−/−) are pro-apoptotic, consistent with their cytotoxicity in vitro." (PMID 34298975, 2021). "Our data support the idea that the antimicrobial gene cathelicidin, which is differentially upregulated by CTX in the Atf3 KO macrophages, is an important anti-cancer factor." (PMID 34298975, 2021). "For example, ATF3 has been shown to promote or suppress apoptosis and cell proliferation, which are critical processes for cancer progression." (PMID 33407456, 2021). "Previous studies have confirmed ATF3 can be activated by ROS in several kinds of human cancer cells." (PMID 33390173, 2021). "Functional network analysis showed that ATF3 regulates cytokine receptors and signaling pathways via various cancer-related kinases, miRNAs, and transcription factors." (PMID 33407456, 2021). "In summary, the Atf3 KO lung has a less conducive environment for cancer cells to extravasate or survive, leading to an overall lower lung colonization in the Atf3 KO than WT lungs." (PMID 34298975, 2021). "One key mechanism is the ability of Atf3 to dictate a dichotomous (yin-yang) switch of CTX-treated macrophage: from pro-cancer for WT to anti-cancer for Atf3 KO macrophage." (PMID 34298975, 2021).
cancer (continued). "ATF3 has moved into the limelight within cancer research, where its expression is dysregulated in multiple cancer types; however, its expression and function are contradictory." (PMID 34098867, 2021). "It has been shown that ATF3 negatively regulates the progression of different cancer cells through the modulation of different downstream pathways." (PMID 33539340, 2021). "The negative regulation of ATF3 on Bcl-xL makes cancer cells more sensitive to histone deacetylase inhibitors (HDACi)." (PMID 33921748, 2021). "By inducing integrin β4 nuclear translocation, nuclear integrin β4 can bind to the ATF3 promoter region to activate ATF3 expression, upregulate downstream pro-apoptotic genes, and promote the apoptosis of cancer cells expressing high levels of integrin β4." (PMID 34439865, 2021). "In human melanoma cells and non-small cell lung cancer cells, ATF3 binds to the promoter region of PD-L1 gene to foster expression of PD-L1, leading to evasion of the cancer cells from T cell-mediated cell-killing." (PMID 35052581, 2021). "As expected, cancer cluster-related genes ATF3, PDZK1, VTN and CXCL8 were highly expressed in CDRCC tissues, and patients with high expression of these genes had significantly poor prognosis (P<0.01)." (PMID 33162821, 2020). "To determine if ATF3 contributes to cell sensitivity in response to splicing inhibitors in these human cancer cell lines, we performed siRNA mediated knockdown of ATF3 in HeLa cells." (PMID 33370278, 2020). "There is thus a need of identifying small molecules that can sustainably increase the ATF3 level in cancer cells." (PMID 31796886, 2020). "In the late cancer stage, the activation of Atf3 appeared completely resolved in line with the resolution of DNIC functionality." (PMID 33172040, 2020). "Using tissue-specific gain- or loss-of-function methods is crucial to elucidate the role of ATF3 in the regulation of immune homeostasis, cancer, and glucose and adipose tissue metabolism." (PMID 32922364, 2020). "Due to its potential dual role, ATF3 has been found to have different effects on cancer progression." (PMID 33050633, 2020). "Overexpression of miR-590-3p decreases cancer cell proliferation and increases apoptosis via downregulation of the expression of ATF3 and Runx2 in MDA-MB231 cells." (PMID 32922364, 2020). "Another report showed that ATF3 overexpression is able to promote cancer-initiating features in immortalized mammary epithelial MCF10A cells via the TGFβ pathway." (PMID 33050633, 2020). "As Atf3−/− mice, unlike Atf4−/− mice, are developmentally normal, drugging ATF3 would be a better strategy than targeting ATF4 for harnessing ferroptosis to treat human diseases including cancer." (PMID 31273299, 2020). "Previous studies have shown that ATF3 expression is correlated with cancer cell death or suppressor of cell growth and metastasis in HCT116 cells." (PMID 29966001, 2018). "Depending on the cellular context or cancer cell type, ATF3 reportedly exhibits a dichotomous role in determining cancer cell fate." (PMID 29966001, 2018). "Although aberrant ATF3 expression is frequently found in human cancers, it is imperative to explore the function and mechanism of this gene, particularly in HCC." (PMID 30376856, 2018). "The ATF3 gene is localized to the 1q amplicon, which is the most amplified chromosomal segment in human cancer." (PMID 30246803, 2018). "Rather, it is the expression of Atf3 in the non-cancer stromal cells—specifically the mononuclear immune cells—that correlated with worse outcome." (PMID 30373101, 2018). "ATF3 is involved in various physiological and pathological functions, acting as a tumor suppressor or oncogenic gene in various cancers and regulating glucagon and insulin levels." (PMID 29515366, 2018).